OGDHL (oxoglutarate dehydrogenase L)
Description:
2-oxoglutarate dehydrogenase (E1-like) component of the 2-oxoglutarate dehydrogenase multienzyme complex (OGDHC) which mediates the decarboxylation of alpha-ketoglutarate in the tricarboxylic acid cycle. The OGDHC complex catalyzes the overall conversion of 2-oxoglutarate to succinyl-CoA and CO(2) while reducing NAD(+) to NADH (By similarity). The OGDHC complex is mainly active in the mitochondrion (By similarity). Involved in the inhibition of cell proliferation and in apoptosis.
Synonyms: FLJ10851; YOBELN
Tractability: PROTAC: ubiquitination databases record sites on it; its protein half-life has been measured.
Gene: Protein-coding gene on chromosome 10 (49,734,641 to 49,762,392, reverse strand). Ensembl gene ENSG00000197444.
Subcellular location: Mitochondrion matrix
Subcellular location (Human Protein Atlas): Nucleoli fibrillar center
Gene Ontology:
Molecular function: protein binding; oxoglutarate dehydrogenase (succinyl-transferring) activity; oxidoreductase activity, acting on the aldehyde or oxo group of donors, disulfide as acceptor; thiamine pyrophosphate binding
Biological process: 2-oxoglutarate metabolic process; tricarboxylic acid cycle
Cellular component: mitochondrial matrix; mitochondrion; oxoglutarate dehydrogenase complex
Genetic constraint (gnomAD): Loss-of-function variants: 79 observed, 112.42 expected, observed/expected ratio (o/e) 0.7, 90% interval 0.58 to 0.85. The upper end of that interval is the gene's LOEUF score, 0.85, which puts it in group 3 of 6, group 1 being the genes least tolerant of losing a copy. Missense variants: 1,275 observed, 1,405.8 expected, observed/expected ratio (o/e) 0.91, 90% interval 0.87 to 0.95. Synonymous variants: 528 observed, 557.6 expected, observed/expected ratio (o/e) 0.95, 90% interval 0.88 to 1.02.
Homologues: Orthologues: chimpanzee OGDHL (99% identical), macaque OGDHL (96% identical), dog OGDHL (95% identical), rabbit OGDHL (94% identical), mouse Ogdhl (93% identical), rat Ogdhl (92% identical), guinea pig OGDHL (92% identical), pig OGDHL (90% identical), tropical clawed frog ogdhl (83% identical), zebrafish ogdhl (78% identical), Drosophila melanogaster Ogdh (61% identical), Caenorhabditis elegans ogdh-1 (55% identical), and 1 more. Paralogues in human: OGDH (77% identical), DHTKD1 (36% identical).
Diseases named in the same sentence as OGDHL in open-access papers:
OGDHL is named in the same sentence as 50 diseases in open-access papers, as found by Europe PMC text mining. Sharing a sentence is not in itself a finding about the gene and the disease. The quoted sentences say what the papers report.
hepatocellular carcinoma (6 papers, 2021 to 2025). A malignant tumor that arises from hepatocytes. "Inhibition of glutamine metabolism improves sorafenib Chemosensitization in oxoglutarate dehydrogenase-like (OGDHL)-deficient hepatoma cells." (PMID 36532884, 2022). "The function of OGDHL has been extensively studied in the liver, particularly in the context of hepatocellular carcinoma (HCC)." (PMID 41463550, 2025). "For instance, OGDHL has been identified as a prognostic biomarker for hepatocellular carcinoma due to its role in reprogramming glutamine metabolism." (PMID 37950065, 2023). "Beyond hepatocellular carcinoma (HCC), studies have demonstrated that OGDHL expression is frequently silenced by cancer-specific promoter methylation in lung, breast, cervix, esophagus, pancreas, renal cell carcinoma and colon cancers." (PMID 41463550, 2025).
pancreatic cancer (6 papers, 2016 to 2025). "Down-regulation of OGDHL expression is correlated with poor prognosis in patients with pancreatic cancer." (PMID 33903282, 2021). "The promoter hypermethylation in OGDHL gene was also observed in breast, cervix, lung, oesophagus, and pancreas cancers." (PMID 28105922, 2016). "Moreover, SRSF6 reportedly increases the inclusion of OGDHL exon 3, thereby affecting pancreatic cancer cell metastasis." (PMID 36064747, 2022). "OGDHL is involved in the tricarboxylic acid cycle, and frequently down-regulated in human carcinoma and suppresses tumor growth, which could be a predictive factor for worse prognosis in patients with pancreatic cancer." (PMID 36838582, 2023). "have found the prognostic value of the combination of oxoglutarate dehydrogenase like (OGDHL), TWIST1 and miR-214 in predicting pancreatic cancer patients." (PMID 35651786, 2022). "MiR-193 a-5p regulates oxoglutarate dehydrogenase-like (OGDHL) and extracellular matrix protein 1 (ECM 1) alternative splicing by targeting SRSF 6, which triggers epithelial-mesenchymal transition (EMT) and consequently enhances pancreatic cancer progression." (PMID 40129567, 2025).
breast carcinoma (5 papers, 2012 to 2023). "Studies have shown that methylation of the OGDHL promoter contributes to the development of many cancers such as breast cancer 11 and colon cancer." (PMID 33405394, 2021). "Subsequent studies focused on the relationship of OGDHL expression in several cancers and reported low expression in breast cancer, cervical cancer, and colorectal cancer." (PMID 31781311, 2019). "Subsequent studies examined the downregulation and methylation of OGDHL in breast cancer, cervical cancer, and colorectal cancer." (PMID 31781311, 2019). "We previously reported that OGDHL is down-regulated by promoter hypermethylation in cervical and breast cancer cell lines, and in a substantial portion of primary tumors of these two primary cancer types." (PMID 23152800, 2012). "Similarly, in breast cancer and sporadic colorectal cancer, abnormal hypermethylation of the OGDHL gene promoter also promotes cancer progression." (PMID 33405394, 2021).
cervical cancer (5 papers, 2012 to 2019). A primary or metastatic malignant neoplasm involving the cervix. "OGDHL was found to suppress cervical tumorigenesis via inactivation of the AKT signaling pathway in cervical cancer." (PMID 31886185, 2019). "It has been pointed out that the re- expression of OGDHL can induce apoptosis in cervical cancer cells." (PMID 30289891, 2018). "It has been shown that re-expression of OGDHL induced apoptosis through a PI3K/AKT pathway in cervical cancer cells." (PMID 28105922, 2016). "To address this question, we determined the protein levels and phosphorylation state of key components of the AKT signaling cascade, using cervical cancer cell lines with either the forced expression or knock-down of OGDHL." (PMID 23152800, 2012). "Knockdown of OGDHL expression in cervical cancer cells expressing endogenous OGDHL had the opposite effect." (PMID 23152800, 2012). "Several lines of evidence suggest that ROS play an essential role in OGDHL–mediated apoptosis in cervical cancer cells." (PMID 23152800, 2012). "In summary, our study shows that OGDHL induces apoptosis of cervical cancer cells via an AKT-dependent pathway." (PMID 23152800, 2012). "Taken together, these data support the notion that OGDHL has anti-proliferative properties in cervical cancer cell lines." (PMID 23152800, 2012). "Little is known, however, about the functional role of the AKT pathway in mediating OGDHL– induced ROS production in human cervical cancer cells." (PMID 23152800, 2012). "Data from caspase-3 activity assay and caspase 3 and poly-ADP-ribose polymerase (PARP) protein cleavage immunoblotting analysis also indicated that OGDHL overexpression induced apoptosis in cervical cancer cells that lack expression of OGDHL." (PMID 23152800, 2012). "In the present study, we have shown that OGDHL negatively regulates cell proliferation by inducing apoptosis in cervical cancer cells." (PMID 23152800, 2012). "The results of the present study show that AKT inactivation is a consequence of OGDHL–mediated ROS production and makes a key functional contribution to the lethality of human cervical cancer cells." (PMID 23152800, 2012). "In depth molecular studies for any gene (here OGDHL) that altered in cervical cancer will help to develop personalized therapy in future." (PMID 23152800, 2012). "Taken together, our findings indicate that down-regulation of OGDHL promotes cervical cancer cell proliferation and survival." (PMID 23152800, 2012). "The level of natural OGDHL methylation was generally low in the cervical cancer cell lines tested in the present study." (PMID 23152800, 2012). "SiRNA knockdown of OGDHL leads to decreased ROS production in two cervical cancer cell lines and significantly inhibits OGDHL–induced cell death." (PMID 23152800, 2012). "These cumulative data suggest that the increased oxidative stress followed by caspase 3-mediated AKT cleavage may be a mechanism by which the activation of this survival pathway is censored in cervical cancer cell lines by forced expression of OGDHL." (PMID 23152800, 2012). "Hence, OGDHL has potential therapeutic applications in cervical cancer through inhibition of NF-κB signaling." (PMID 23152800, 2012). "We over expressed OGDHL in siRNA knockdown phenotype of cervical cancer cell lines." (PMID 23152800, 2012). "To investigate the significance of long term effect of OGDHL re-expression in a cervical cancer cell line, we generated OGDHL over-expressing stable clones using SiHa cell line and compared the functional and molecular differences of this cell line with the stable clones containing vector only." (PMID 23152800, 2012). "Thus, having determined that OGDHL is frequently methylated, we examined its potential tumor suppressor function in cervical cancer cell lines." (PMID 23152800, 2012). "Furthermore, altering the promoter methylation by treatment with a demethylating agent (5-Azacytidine) in cervical cancer cell lines led to re-expression of OGDHL." (PMID 23152800, 2012).
cervical cancer (continued). "However we found about 20% incidence of OGDHL methylation in cervical cancer, and we thus presume that at least some cervical cancers may develop due to inactivation of the OGDHL gene by promoter methylation and activation of the AKT- NF-κB pathway." (PMID 23152800, 2012). "Here, we showed that OGDHL modulates AKT signaling in cervical cancer cell lines, and thus our results suggest that OGDHL may have biologic importance in initiation and progression of cervical cancer and it may be use as a biomarker for the management of cervical cancer." (PMID 23152800, 2012). "Taken together, these data suggest that inactivation of OGDHL can contribute to cervical tumorigenesis via activation of the AKT signaling pathway and thus support it as an important anti-proliferative gene in cervical cancer." (PMID 23152800, 2012). "Here, we report that restoration of OGDHL expression in cervical cancer cells lacking endogenous OGDHL expression suppressed cell proliferation, invasion and soft agar colony formation in vitro." (PMID 23152800, 2012). "Interestingly, our findings show that over-expression of OGDHL in cervical cancer cell lines blocks AKT activation and inhibit cervical cancer cell proliferation and survival." (PMID 23152800, 2012). "Moreover, the addition of caspase 3 or ROS inhibitors in the presence of OGDHL increased AKT signaling and cervical cancer cell proliferation." (PMID 23152800, 2012). "We have tested the PI3K/AKT signaling in cervical cancer cell lines with different baseline levels of OGDHL expression, which may not necessarily reflect the behavior of primary tumors." (PMID 23152800, 2012).
liver cancer (5 papers, 2019 to 2022). An epithelial or non-epithelial malignant neoplasm that arises from the liver. "We examined the role of altered OGDHL expression in liver cancer and determined its value as a diagnostic and prognostic indicator for patients." (PMID 31781311, 2019). "This study is the first to identify OGDHL as a novel diagnostic and prognostic biomarker for liver cancer." (PMID 31781311, 2019). "We also found that OGDHL expression had value as a diagnostic and prognostic indicator of liver cancer and that low OGDHL expression was an independent prognostic risk factor." (PMID 31781311, 2019). "However, a limitation of this study is that we only examined a small number of patients with advanced-stage liver cancer; the cause of higher OGDHL expression in late stage liver cancer patients needs to be explored in the future study." (PMID 31781311, 2019). "OGDHL has potential as a diagnostic and prognostic biomarker for liver cancer." (PMID 31781311, 2019). "This study is the first to identify the diagnostic and prognostic value of OGDHL in liver cancer, and our results indicate that OGDHL might be useful as a novel biomarker for liver cancer." (PMID 31781311, 2019). "In addition, our multivariable analysis indicated that low OGDHL expression was a significant diagnostic and prognostic biomarker for liver cancer." (PMID 31781311, 2019). "Moreover, our ROC analysis showed that OGDHL expression had good diagnostic performance for patients with different stages of liver cancer, supporting its clinical use as a diagnostic biomarker." (PMID 31781311, 2019). "Lately, Dai showed that knockout of OGDHL in liver cancer cells stimulated the consumption of glutamine which is a precursor substance necessary for the synthesis of glutathione and an effective antioxidant." (PMID 35463769, 2022). "On the contrary, the low mRNA expression of oxoglutarate dehydrogenase-like (OGDHL) and phosphoglucomutase-like protein 5 (PGM5) was associated with poor prognosis for liver cancer." (PMID 32420386, 2020). "However, the diagnostic value, prognostic value, and role of OGDHL in liver cancer remain unknown." (PMID 31781311, 2019). "We found that patients with liver cancer who had lower OGDHL expression had shorter OS and shorter relapse-free survival." (PMID 31781311, 2019). "In the present study, we found that OGDHL had low expression in liver cancer and that low expression correlated with more advanced patient age, histologic grade, stage, T classification, and shorter survival." (PMID 31781311, 2019). "In conclusion, we found low expression of OGDHL in liver cancer and that low expression correlated with advanced patient age, histologic grade, stage, T classification, and poor survival." (PMID 31781311, 2019). "We also examined the correlation of OGDHL expression with clinical features and performed survival analysis using the Cox model to assess its function as an independent prognostic indicator in liver cancer." (PMID 31781311, 2019). "The down-regulation of OGDHL and IDH genes in liver cancer tissue will lead to the metabolic activity of the tricarboxylic acid cycle, even reversal of the TCA cycle." (PMID 36324575, 2022). "OGDHL is also a promising prognostic biomarker and a potential therapeutic target for OGDHL-negative liver cancer." (PMID 36407768, 2022).
developmental delay (3 papers, 2023 to 2025). "Mutations in OGDHL are linked to a broad spectrum of neurodevelopmental disorders, characterized by developmental delay, intellectual disability, epilepsy, corpus callosum dysgenesis, and sensory deficits." (PMID 41463550, 2025). "The homozygous or compound heterozygous mutations in the OGDHL gene would cause Yoon-Bellen neurodevelopmental syndrome, which is characterized by developmental delay with varying degrees of impaired intellectual development." (PMID 38784233, 2024).
glioma (3 papers, 2022 to 2025). A benign or malignant brain and spinal cord tumor that arises from glial cells (astrocytes, oligodendrocytes, ependymal cells). "Then, four genes (IL4I1, CYP1A1, OGDHL, and ASMT) were screened out by univariate and multivariate cox regression analysis of tryptophan metabolism genes, and a risk score model for predicting the overall survival (OS) of glioma patients was constructed." (PMID 36407768, 2022). "Immune-related pathways such as TNF signalling (IDH3B/G, MDH1, ACO2, SDHA, OGDHL) and JAK/STAT3 (PIAS2/3, PTPN2, AKT1/2, MCL1, CISH, AOX1) signalling are enriched in gliomas and play a critical role in their progression." (PMID 41007296, 2025). "Among them, the expression of IL4I1 in glioma patients was greater than of normal samples, while the CYP1A1, OGDHL, and ASMT were lower in glioma samples." (PMID 36407768, 2022). "The construction of our predictive model was based on the expression levels of four genes (IL4I1, CYP1A1, OGDHL, and ASMT) in glioma tissues." (PMID 36407768, 2022). "Combined with the results of our univariate Cox analysis, we can conclude that IL4I1 plays a tumor-promoting role and CYP1A1, OGDHL, and ASMT all play protective roles in gliomas." (PMID 36407768, 2022). "At the same time, we verified the expression of IL4I1, CYP1A1, OGDHL, and ASMT four genes in glioma specimens and cell lines in GES4260 and GES15824." (PMID 36407768, 2022). "We found that IL4I1 was highly expressed in glioma cell lines (LN018, LN215, LN229, and LN319), CYP1A1 was low expressed in glioma cell lines (LN215, LN229, LN319, and BS149), OGDHL was low expressed in LN018, and ASMT was lowly expressed in glioma cell lines (LN018, LN215, LN229, LN319, and BS149)." (PMID 36407768, 2022).
ovarian carcinoma (3 papers, 2022 to 2024). A malignant neoplasm originating from the surface ovarian epithelium. "Afterward, univariate Cox regression analysis was performed to evaluate the prognostic value of each tryptophan metabolism-related gene in the TCGA ovarian cancer cohort, with IDO1, ALDH3A2, HADHA, OGDHL associated with risk values, and CAT, WARS1 involved in protective factors." (PMID 38468343, 2024). "Additionally, OGDHL is upregulated in epithelial ovarian cancer tumor samples compared with controls but downregulated by both kaempferol and progesterone treatments." (PMID 36986136, 2023).
colorectal cancer (2 papers, 2019). A primary or metastatic malignant neoplasm that affects the colon or rectum. "A significant high methylation level leading to inactivation of OGDHL was observed in colorectal cancer compared with nontumoral marginal samples and might be considered as a biomarker for colorectal carcinogenesis." (PMID 31886185, 2019).
epilepsy (2 papers, 2023 to 2025). A brain disorder characterized by episodes of abnormally increased neuronal discharge resulting in transient episodes of sensory or motor neurological dysfunction, or psychic dysfunction. "Mutations in the human gene OGDHL cause a neurodevelopmental spectrum disease featuring epilepsy." (PMID 36873106, 2023). "Such an approach has already led to the functional description of many epilepsy-related variants in single genes, for example by utilizing T2A-GAL4 technology and UAS-transgenes carrying either wild-type or gene variant for the gene OGDHL." (PMID 36873106, 2023).
Yoon-Bellen neurodevelopmental syndrome (2 papers, 2023 to 2024). "In proband BR1, the heterozygous deletion did not contain dominant disease genes, but three recessive genes (SLC38A1, CHAT and OGDHL) with a muscle phenotype: congenital myasthenic syndrome type 21 or type 6, or Yoon-Bellen neurodevelopmental syndrome, respectively." (PMID 36781956, 2023).
Abdominal obesity (1 paper, 2020). Excessive fat around the stomach and abdomen. "Abdominal obesity was significantly associated with rectal cancer among noncarriers of SUCLG2-rs35494829 (1.35 [1.12–1.63]), OGDHL-rs11101224 (1.37 [1.12–1.68]), and OGDHL-rs751595 (1.40 [1.14–1.72])." (PMID 33053772, 2020).
Alzheimer disease (1 paper, 2022). A progressive, neurodegenerative disease characterized by loss of function and death of nerve cells in several areas of the brain leading to loss of cognitive function such as memory and language. "For example, an early study proposed that OGDHL might be linked to neurotransmitter synthesis and Alzheimer's disease." (PMID 35370858, 2022).
Ascites (1 paper, 2022). Accumulation of fluid in the peritoneal cavity (between the layers of the peritoneum that lines the abdomen). "In schistosomiasis clinical signs, ITIH4 at 3p21.1 (index rs2239548) was associated with portal vein diameter (PVD) class, an indicator of portal hypertension, and OGDHL at 10q11.23 (index rs1258172) was related to ascites grade." (PMID 35493725, 2022).